FASLG (Fas ligand)
Diseases named in the same sentence as FASLG in open-access papers (continued):
Sharing a sentence is not in itself a finding about the gene and the disease.
ischemic stroke (15 papers, 2013 to 2025). A stroke disorder caused by obstruction of blood flow to the brain, due to thrombotic (local blood clot formation) or embolic (due to a blood clot or other material traveling from another site) event. "Levels of this microRNA increased following ischemic stroke secondary to decreased Fas ligand (FasL) G, a cell death-inducing ligand." (PMID 34044272, 2021). "During ischaemic stroke, the expression of genes such as the Fas ligand (FasL) is upregulated." (PMID 37987924, 2024).
bladder cancer (14 papers, 2005 to 2024). "In fact, the occurrence and progression of cancer is not always caused by abnormal gene expression, but our results further demonstrate the reliability of the FASLG gene as a prognostic biomarker gene for bladder cancer." (PMID 35174173, 2021). "Furthermore, the hub gene FASLG of Luminal-papillary and Neuronal encodes the FasL protein, on the other hand, the prognostic value of soluble FasL (sFasL) in the serum of bladder cancer patients has been investigated." (PMID 34852762, 2021). "The soluble Fas ligand (sFasL) was strongly expressed in TTC and moderately expressed in bladder cancer cells." (PMID 37891379, 2024). "Through univariate and multivariate Cox proportional hazard regression analysis, we concluded that FASLG and PRKCZ can be used as prognostic biomarkers for bladder cancer." (PMID 35174173, 2021). "Amentoflavone markedly inhibits TSGH-8301 bladder cancer cell activity via the induction of mitochondria-dependent intrinsic apoptosis and Fas cell surface death receptor (FAS)/FAS ligand (FASL)-dependent extrinsic apoptosis." (PMID 33996570, 2021). "Treatment with cisplatin increased the level of the membrane-bound Fas ligand (FasL) in the TTC (833 K, SuSa and GCT27), while no FasL could be detected in the bladder cancer cell lines." (PMID 37891379, 2024).
Lymphadenopathy (14 papers, 2011 to 2023). Enlargement (swelling) of a lymph node. "Mice, exclusively expressing the soluble form of FasL, develop lymphadenopathy due to lack of selective immune cell-induced apoptosis usually performed by the membrane form of Fas ligand." (PMID 33671651, 2021).
Obesity (14 papers, 2017 to 2025). Accumulation of substantial excess body fat. "The novel finding of significantly reduced Fas-ligand (FasL) levels reported here is linked to obesity; increased expression of FasL has been associated with adipocyte hypertrophy and macrophage infiltration in adipose tissue, for example." (PMID 27525640, 2017). "Obesity also increases the concentration of CXCL1, promotes CXCR2 mediated Fas ligand (FasL) activation, and recruitment of MDSCs, leading to apoptosis of CD8+ T cells and decreased immunotherapy efficiency." (PMID 39712006, 2024). "Obesity has been reported to increase CXCL1 concentrations in the BC microenvironment, contributing to CXCR2-mediated chemotaxis and the accumulation of G-MDSCs expressing the Fas ligand (FasL)." (PMID 37465670, 2023).
B cell lymphomas (13 papers, 2012 to 2025). "E.g., a genome-wide CRISPR/Cas9 screen identified the necessary role for FAS/FASLG in CD19-directed CAR T cell killing in an in vivo model of B cell lymphoma." (PMID 39843653, 2025). "Cell membrane nucleolin interacts with Fas receptor to prevent Fas-induced apoptosis activated by Fas ligand (FAS-L) in B-cell lymphoma cells." (PMID 39125875, 2024). "MemNCL interacts with Fas receptor to prevent Fas-induced apoptosis activated by Fas-ligand (FAS-L) in B cell lymphoma cells." (PMID 35861882, 2022).
liver disease (13 papers, 2011 to 2023). "Accuracy of serum Fas-ligand and GGT levels for predicting acute decompensation in the follow-up of patients with compensated liver disease was high (AUC = 0.79, p < 0.001)." (PMID 35176084, 2022).
myocardial infarction (13 papers, 2011 to 2025). Gross necrosis of the myocardium, as a result of interruption of the blood supply to the area, as in coronary thrombosis. "Fas ligand (FASLG) is a member of the tumor necrosis factor superfamily and major activator of apoptotic pathways binding to tumor necrosis factor receptors during myocardial infarction." (PMID 34777632, 2021).
neutropenia (13 papers, 2013 to 2025). A decrease in the number of neutrophils found in the blood. "Confirming the well-known heterogeneity of T-LGL leukemia, this study, performed in a large cohort of patients, provides evidence for a link between biological markers (phenotype, STAT3 mutations and activation, Fas ligand production) and neutropenia." (PMID 28977911, 2017). "The mechanism of neutropenia is multifactorial but most likely involves the secretion of pro-inflammatory cytokines, possibly through a Fas/Fas-ligand (Fas-L) dependent mechanism." (PMID 38610985, 2024). "STAT3 acts as a transcription factor with anti-apoptotic as well as proliferative effects and additionally, its activation in T-LGL leukemia patients correlates with FasL (Fas ligand) levels, explaining the occurrence of neutropenia in these patients." (PMID 37920595, 2023). "Liu and co-workers showed that neutropenia in LGL leukemia patients was consequent to the high level of circulating Fas ligand produced by LGLs, since neutrophils undergo apoptosis through Fas triggering." (PMID 28977911, 2017). "In conclusion, our data show that T-LGL leukemia with specific molecular and phenotypic patterns is associated with discrete clinical features contributing to get insights into molecular bases accounting for the development of Fas ligand-mediated neutropenia." (PMID 28977911, 2017). "Since normal neutrophil survival is partly regulated by the Fas-Fas ligand apoptotic system, it is suggested that LGL leukemia neutropenia might be mediated by deregulated expression of Fas ligand." (PMID 28977911, 2017). "Since secreted Fas ligand, which is increased in the serum of patients affected by T-LGL leukemia, has been hypothesized to play a role in inducing neutropenia in these patients, we evaluated Fas ligand expression in our series of patients subdivided according to their immunophenotype." (PMID 28977911, 2017). "Published data suggests that late onset neutropenia could be related to an excess of T-lymphocyte populations which express and secrete large amounts of Fas and Fas Ligand (FasL) leading to the apoptosis of mature neutrophils and the production of antineutrophil autoantibodies." (PMID 24109519, 2013). "To get insights into the molecular bases of neutropenia in these patients, we demonstrated a link between STAT3 phosphorylation and Fas ligand transcription levels." (PMID 28977911, 2017). "The evidence that CD8+/CD16+/CD56- patients were characterized by higher level of Fas ligand, as a consequence of their higher STAT3 phosphorylation, offers a mechanistic explanation for the correlation between STAT3 activation and neutropenia." (PMID 28977911, 2017). "Moreover, there is a certain correlation between the soluble Fas ligand concentration and the depth of neutropenia in LGL leukemia, suggesting that the soluble Fas ligand plays a role in neutrophil apoptosis." (PMID 35178350, 2022).
oral cancer (12 papers, 2013 to 2024). "Quercetin treatment induced apoptosis in human oral cancer SAS cells by increasing the expression of Fas, Fas-Ligand, and caspase-8." (PMID 32093300, 2020). "Suberoylanilide hydroxamic acid (SAHA) markedly enhanced the expressions of DR4, DR5, Fas cell surface death receptor (Fas), and the Fas ligand (FasL; FASLG) in oral cancer Ca9-22 and SAS cells." (PMID 28708091, 2017).
acute respiratory distress syndrome (11 papers, 2010 to 2022). Progressive and life-threatening pulmonary distress in the absence of an underlying pulmonary condition, usually following major trauma or surgery. "Additionally, the PCR array showed upregulation of other influential molecules such as Fas/Fas ligand, which is important in the development of fibrotic lesions associated with adult respiratory distress syndrome (ARDS)." (PMID 24143891, 2013). "The Fas-Fas ligand (FasL) pathway has been demonstrated to contribute to severe epithelial damage that occurs in the acute respiratory distress syndrome (ARDS), a disease characterized by the death of lung epithelial cells with resultant loss of lung barrier function." (PMID 24658576, 2014).
endometriosis (11 papers, 2014 to 2025). The growth of functional endometrial tissue in anatomic sites outside the uterine body. "In endometrial stromal cells IL8 has also been shown to up-regulate Fas ligand (FasL) expression which promoted cytotoxic T lymphocytes apoptosis, a mechanism considered to serve as mediator of local immunotolerance in endometriosis." (PMID 24755559, 2014). "Increased IL-8 levels in the endometriosis peritoneal microenvironment can upregulate Fas-ligand (FasL) expression in endometrial cells and induce cytotoxic T lymphocyte apoptosis, potentially establishing a local immune tolerance environment for ectopic endometrial implantation." (PMID 36762287, 2023). "The presence of both forms of the Fas ligand (soluble and membrane-bound) in the peritoneal fluid of women with endometriosis seen in cited works, in comparison with our results, may suggest increased immune cell apoptosis in the peritoneal cavity." (PMID 29226157, 2017).
injury (11 papers, 2010 to 2022). Damage inflicted on the body as the direct or indirect result of an external force, with or without disruption of structural continuity. "Recently it has been point out that Fas-Fas ligand (FasL) signaling plays a central role in acute inflammation (e.g. acute lung injury)." (PMID 20175894, 2010). "Importantly, deletion of myeloid FASLG or neutralization of FASLG on myeloid cells was reported to improve functional recovery after CNS trauma." (PMID 25284487, 2014).
ischemia (10 papers, 2012 to 2024). A hypoperfusion of the BLOOD through an organ or tissue caused by a PATHOLOGIC CONSTRICTION or obstruction of its BLOOD VESSELS, or an absence of BLOOD CIRCULATION. "SP600125 reduces phosphorylation of c-Jun and the expression of Fas ligand (FasL), induced by ischemia/reperfusion in the region CA1 of the hippocampus." (PMID 30026697, 2018).
asthma (9 papers, 2010 to 2025). "The gene closest to the top SNPs on chromosome 7 is FASLG (Fas Ligand), which has previously been associated with several allergic disorders, including allergic rhinitis, psoriasis, asthma, hay fever, and eczema." (PMID 40612147, 2025).
breast tumors (9 papers, 2000 to 2023). "Breast tumor cells have also been shown to express Fas ligand (FasL)." (PMID 37894728, 2023).
malaria (9 papers, 2007 to 2017). Malaria is a serious and sometimes fatal disease caused by a parasite that commonly infects a certain type of mosquito which feeds on humans. "In this study, we demonstrate that the cytotoxic activity of CD8+ T cells contributes to the protection of mice against blood-stage malaria in a Fas ligand (FasL)-dependent manner." (PMID 25760084, 2015). "Splenic CD8+ T cells activated during malaria express Fas ligand (FasL) and interact with Fas-expressing parasitized erythroblasts." (PMID 25760084, 2015). "Apoptosis in malaria is reportedly mediated by the Fas-ligand in lymphocytes and in murine astrocytes." (PMID 24636003, 2014). "Others have pointed to the increased propensity of lymphocytes from malaria patients to undergo spontaneous apoptosis in vitro, possibly induced by soluble Fas ligand (sFasL)-Fas interaction." (PMID 23506136, 2013). "Although some studies have linked the occurrence of T lymphocyte apoptosis with high levels of soluble Fas ligand (sFasL) in human malaria, the involvement of the Fas/FasL system has not been observed in experimental models of malaria." (PMID 25559491, 2015).
pemphigus (9 papers, 2010 to 2024). Pemphigus is a group of rare autoimmune diseases that cause blistering of the skin and mucous membranes (mouth, nose, throat, eyes, and genitals).This conditioncan occur at any age, but often strikes people in middle or older age. "In particular, cleaved caspase-8 and -3 were detected in pemphigus lesions, and upregulation of Fas ligand (FasL) was observed in keratinocytes co-cultured with PV IgG." (PMID 37180099, 2023). "In particular, cleaved caspase-8 and -3 are detected in keratinocytes of pemphigus lesions, and caspase-8-positive keratinocytes display increased Fas Ligand expression." (PMID 37503332, 2023). "In accordance with this observation, a novel anti-soluble Fas ligand human monoclonal antibody (PC111) has been tested for pemphigus therapy due to its low potential for immunogenicity, favorable chemical and physical stability, and high binding affinity." (PMID 35783635, 2022). "An experimental study showed that soluble Fas ligand, which is upregulated and released from keratinocytes, was believed to play a critical role in blistering in the pemphigus pathogenesis." (PMID 35783635, 2022). "In particular, cleaved caspase-8 and -3 are detected in pemphigus lesions, and caspase-8-positive cells express Fas ligand (FasL)/Fas binding." (PMID 29535737, 2018). "We have shown previously that anti-Fas ligand (FasL) antibody (Ab) prevents PVIgG-induced caspase-8 activation and Dsg cleavage in human keratinocytes, and that sera from pemphigus patients contain abnormally increased levels of FasL." (PMID 29535737, 2018). "Dr Pincelli's group demonstrated that Fas ligand (FasL) in pemphigus sera induces keratinocyte apoptosis through activation of caspase 8, and that FasL neutralizing antibody prevents PV IgG-induced apoptosis both in vitro and in vivo." (PMID 21939410, 2012). "In contrast, other groups have suggested that pemphigus associated apoptosis is independent of changes in Fas-ligand levels." (PMID 20631907, 2010).
thyroid cancer (9 papers, 2009 to 2025). "Additional mechanism studies including FAS and FASLG are needed to define the risk of thyroid cancer in AT/AU patients." (PMID 29950587, 2018). "For example, soluble Fas ligand is identified as a biomarker of thyroid cancer recurrence and may be useful for risk-adapted surveillance strategies in thyroid cancer patients." (PMID 24949464, 2014). "Circulating FASLG in cancer has been seen before, where a correlation with thyroid cancer recurrence was demonstrated." (PMID 32606315, 2020).
type 1 diabetes (9 papers, 2012 to 2025). "Guo developed an algorithm for identifying steering nodes to a gene regulatory network related to type 1 diabetes and they found that FASLG and CD80 are steering nodes for controlling the target nodes related to type 1 diabetes and supported by wet experiments." (PMID 33968733, 2021). "Fas ligand drives insulitis in the non-obese diabetic mouse model of type 1 diabetes (T1D) and negatively regulates IL-10-producing (IL-10pos) CD5+ B cells in pancreata." (PMID 28439273, 2017).
chronic hepatitis (8 papers, 2010 to 2021). An active inflammatory process affecting the liver for more than six months. "The expression of Fas ligand was up-regulated in the hepatocytes of patients with chronic hepatitis." (PMID 20727132, 2010).
oral squamous cell carcinoma (8 papers, 2013 to 2025). "Apoptosis of effector cytotoxic T cells, observed in the peripheral circulation of patients with oral squamous cell carcinoma, was found to be mediated through FasL (Fas ligand) positive EVs." (PMID 29760691, 2018).
viral hepatitis (8 papers, 2004 to 2025). An acute or chronic inflammation of the liver parenchyma caused by viruses. "During fulminant viral hepatitis, a cytokine burst arises, resulting in an enrichment of the hepatic microenvironment in death factors such as TNF-α, Fas ligand (FasL) or TRAIL." (PMID 30622241, 2019).
esophageal cancer (7 papers, 2012 to 2022). A primary or metastatic malignant neoplasm involving the esophagus. "In contrast, the high expression of TLR3 in KIRC, ACC, MESO, esophageal carcinoma (ESCA), and uterine carcinosarcoma (UCS); FASLG in HNSC, BLCA, and STAD; RIPK3 in COAD; RIPK1 in MESO and KIRP; FAS in ACC; and FADD in THCA was associated with good survival." (PMID 35748782, 2022).
head and neck cancer (7 papers, 2011 to 2024). A primary or metastatic malignant neoplasm affecting the head and neck. "According to in vitro and in vivo evidence, FASLG targeted gene therapy could suppress the tumor growth in head and neck cancer." (PMID 38356704, 2024).
LGL leukemia (7 papers, 2017 to 2024). "Constitutive activation of STAT3 and production of IL6 induce an increase in the transcription and expression of Fas ligand in LGL leukemia." (PMID 35178350, 2022). "STAT3 is a driver of soluble Fas ligand (sFasL) expression in LGLs, and sFasL is present at high levels in LGL leukemia patient serum." (PMID 35646651, 2022). "Consistently, high levels of circulating Fas ligand have been detected in T-LGL leukemia serum, likely triggering neutrophil apoptosis through the production of secreted Fas ligand." (PMID 28977911, 2017). "The difference of Fas ligand production observed on transcriptional expression was also confirmed by ELISA measuring Fas ligand level in patients’ plasma (CD16+/CD56- CD8+ T-LGL leukemia: 88.3 ± 14.18 pg/ml, the other CD8+ and CD4+ immunophenotypes: 16.08 ± 14.62 pg/ml, P < 0.0001)." (PMID 28977911, 2017). "Consistently, when we triggered STAT3 phosphorylation with IL-6 (20 ng/ml) or IL-15 (20 ng/ml), key cytokines in LGL leukemia development, after one hour culture we observed an increase of Fas ligand transcription levels (1.59- and 2.01-fold after IL-6 and IL-15, respectively)." (PMID 28977911, 2017).
Nephropathy (7 papers, 2010 to 2023). A nonspecific term referring to disease or damage of the kidneys. "The function of MMP-7 in renal disorders is multifaceted: it can exhibit protective function in acute kidney injury by degrading E-cadherin and Fas-Ligand (a TNF family protein)." (PMID 37626956, 2023). "Here, we investigated cisplatin-induced oxidative renal damage and tested the hypothesis that ROS-dependent shedding of death activator Fas ligand (FasL) occurs in cisplatin nephropathy." (PMID 29619879, 2018).
retinal detachment (7 papers, 2013 to 2023). An eye emergency condition which may lead to blindness if left untreated. "661W cells die via caspase-mediated mechanisms, and the Fas-ligand (FasL) treatment of these cells leads to the activation of caspases and subsequent death, analogous to the in vivo experimental retinal detachment model." (PMID 37242488, 2023). "Fas ligand (FasL) triggers apoptosis of Fas-positive cells, and previous reports described FasL-induced cell death of Fas-positive photoreceptors following a retinal detachment." (PMID 26583327, 2015). "In support of this hypothesis is the finding that this apoptotic pathway, including FAS, FASLG, and CASP8, are activated in Brown-Norway rats after retinal detachment." (PMID 24367709, 2013).
T cell lymphoma (7 papers, 2006 to 2026). "However, ezrin was also suggested, in another study, to inhibit TRAIL- and Fas ligand-induced cell death in T cell lymphomas." (PMID 26010871, 2015). "While the contribution of ezrin in Fas signalling has been extensively studied, little is known regarding TRAIL, with the exception of a recent study in which ezrin was proposed to impair both Fas ligand- and TRAIL-induced cell death in the tumor T-cell lymphoma cell line H9." (PMID 26010871, 2015).
tuberculosis (7 papers, 2012 to 2023). A chronic, recurrent infection caused by the bacterium Mycobacterium tuberculosis. "In our study, soluble CD30 and FASLG were also markedly up-regulated in the plasma of tuberculosis patients (data not shown)." (PMID 22719887, 2012).